SPINK6 (serine peptidase inhibitor Kazal type 6)
Description:
Serine protease inhibitor selective for kallikreins. Efficiently inhibits KLK4, KLK5, KLK6, KLK7, KLK12, KLK13 and KLK14. Doesn't inhibit KLK8.
Synonyms: MGC21394; UNQ844; BUSI2
Tractability: Antibody: its Gene Ontology location is reachable by antibodies, with high confidence; UniProt places it where antibodies can reach, with medium confidence; UniProt predicts a signal peptide or a membrane-spanning region.
Gene: Protein-coding gene on chromosome 5 (148,202,794 to 148,215,137, forward strand). Ensembl gene ENSG00000178172.
Subcellular location: Secreted
Pathways (Reactome):
Developmental Biology: Formation of the cornified envelope
Gene Ontology:
Molecular function: serine-type endopeptidase inhibitor activity
Biological process: negative regulation of proteolysis
Cellular component: extracellular region
Genetic constraint (gnomAD): Loss-of-function variants: 8 observed, 7.48 expected, observed/expected ratio (o/e) 1.07, 90% interval 0.62 to 1.78. That is too few expected variants to judge how well the gene tolerates losing a copy. Missense variants: 77 observed, 75.11 expected, observed/expected ratio (o/e) 1.03, 90% interval 0.85 to 1.24. Synonymous variants: 16 observed, 26.45 expected, observed/expected ratio (o/e) 0.6, 90% interval 0.41 to 0.92.
Homologues: Orthologues: chimpanzee SPINK6 (99% identical), macaque SPINK6 (95% identical), pig SPINK6 (84% identical), dog SPINK6 (80% identical), mouse Spink6 (78% identical), rat Spink6 (78% identical), guinea pig SPINK6 (76% identical), rabbit SPINK6 (76% identical). Paralogues in human: SPINK5 (48% identical), FST (31% identical), FSTL4 (24% identical), FSTL5 (24% identical), FSTL1 (14% identical), FSTL3 (14% identical).
Diseases named in the same sentence as SPINK6 in open-access papers:
SPINK6 is named in the same sentence as 18 diseases in open-access papers, as found by Europe PMC text mining. Sharing a sentence is not in itself a finding about the gene and the disease. The quoted sentences say what the papers report.
nasopharyngeal carcinoma (7 papers, 2016 to 2025). A carcinoma arising from the nasopharyngeal epithelium. "SPINK6 was linked to pathologies, including skin barrier function and metastasis of nasopharyngeal carcinoma." (PMID 34826211, 2022). "In nasopharyngeal carcinoma, SPINK6 activates EGFR and downstream AKT pathway through a similar domain to EGF, enhancing EMT and thus promoting tumor metastasis." (PMID 39990675, 2025). "As a secreted protein, SPINK6 promotes the metastasis of nasopharyngeal carcinoma cells through autocrine and paracrine mechanisms." (PMID 35223512, 2022). "As a newly identified protease inhibitor, SPINK6 was reported to be involved in skin barrier function and metastasis of nasopharyngeal carcinoma." (PMID 34826211, 2022). "SPINK6, which is overexpressed in tumors and highly metastatic nasopharyngeal carcinoma cells, has been reported as an independent unfavorable prognostic factor." (PMID 34133324, 2021). "Immunohistochemical staining of SPINK6 in nasopharyngeal cancer samples validated the gene panel." (PMID 38157249, 2023). "Importantly, the elevated expression of SPINK6 in primary nasopharyngeal carcinoma is an independent adverse prognostic factor for overall survival, disease-free survival and distant metastasis-free survival of patients." (PMID 35223512, 2022). "SPINK6 could be a prognostic indicator in nasopharyngeal carcinoma patients, and SPINK6 could play a critical role in promoting metastasis of nasopharyngeal carcinoma patients." (PMID 27980454, 2016).
melanoma (3 papers, 2023 to 2025). A malignant, usually aggressive tumor composed of atypical, neoplastic melanocytes. "In melanoma, SPINK6 activates the EGFR/EphA2 complex and downstream ERK1/2 and AKT pathways, thereby promoting tumor metastasis." (PMID 39990675, 2025). "SPINK6 plays an important role in melanoma migration, invasion, and metastasis." (PMID 37369946, 2023). "In melanoma, BRD4 directly interacts with the enhancer of SPINK6 and mediates its expression." (PMID 37369946, 2023).
atopic dermatitis (2 papers, 2017 to 2022). "Immunohistochemical staining has also indicated a reduced SPINK6 expression in atopic dermatitis and psoriasis lesions." (PMID 35982087, 2022). "SPINK6 and SPINK9 are also expressed in the skin, and altered expression levels are associated with atopic dermatitis or psoriasis." (PMID 28554943, 2017).
hepatocellular carcinoma (2 papers, 2017 to 2025). A malignant tumor that arises from hepatocytes. "The apparent lack of KLK14 in the cultural supernatant of hepatocellular carcinoma cells suggested that inhibition of KLK14 is not involved in SPINK6 mediated suppression of tumorigenic phenotypes." (PMID 27999203, 2017).
influenza (2 papers, 2022 to 2025). An acute viral infection of the respiratory tract, occurring in isolated cases, in epidemics, or in pandemics; it is caused by serologically different strains of viruses (influenzaviruses) designated A, B, and C, has a 3-day incubation period, and usually lasts for 3 to 10 days. "For example, higher outdoor temperature was associated with higher SPINK6 levels (maintaining skin homeostasis and restricting influenza activation), and shorter fasting time was associated with higher GIP levels (stimulating insulin secretion)." (PMID 41071435, 2025). "SPINK6‐specific inhibition of HAT, and its native target KLK5 and KLK12, as well as its upregulation upon infection, underscores the importance of SPINK6 in human influenza infection." (PMID 34826211, 2022).
Congenital anonychia (1 paper, 2021). "Single-cell RNAseq with 11,541 cells from 4 extra digits revealed nail-specific mesenchymal and epithelial cell populations, characterized by RSPO4 (major gene in congenital anonychia) and SPINK6, respectively." (PMID 34099859, 2021).
liver cancer (1 paper, 2017). An epithelial or non-epithelial malignant neoplasm that arises from the liver. "Our study has shown that SPINK6 can suppress tumorigenic phenotypes of liver cancer cells in several in vitro models." (PMID 27999203, 2017).
lung adenocarcinoma (1 paper, 2016). A carcinoma that arises from the lung and is characterized by the presence of malignant glandular epithelial cells. "We found that RSPO3, ADAMTS8, DMBT1, DOCK8, STMN2, SPINK6 and TUSC3 were the co-genes of HOXA11-AS in lung adenocarcinoma whereas RSPO3, ADAMTS8, DMBT1, DOCK8, STMN2, SPINK6, TUSC3 and C8orf22 were the co-genes of HOXA11-AS in squamous cell carcinoma." (PMID 27980454, 2016). "For the other five genes (STMN2, SPINK6, TUSC3, LOC100128054, and C8orf22), we found that STMN2, TUSC3 and C8orf22 were upregulated in squamous cell carcinoma and that STMN2 and USC3 were upregulated in lung adenocarcinoma." (PMID 27980454, 2016).
tumor (7 papers, 2017 to 2025). "RNA-seq identified SPINK6 was a downstream gene of BAP31, and was associated with tumor stage and metastasis in HCC." (PMID 39990675, 2025). "Unpaired and paired differential expression analysis results showed that CA9 and SPINK6 have higher expression in tumor tissue (P < 0.05), indicating their involvement in development of OSCC." (PMID 40703658, 2025). "To understand the molecular mechanism of SPINK6-triggered tumor suppression, we analyzed the impact of SPINK6 overexpression on different signaling pathways linked to carcinogenesis in HCC cells." (PMID 27999203, 2017). "The results strongly support the importance of SPINK6 in suppressing tumor formation from injected HCC cells." (PMID 27999203, 2017). "In the presence of 1μM PMA, the phosphorylation of ERK1/2 of different clones were indistinctive, meanwhile the tumor suppression function of SPINK6 seemed to be blocked." (PMID 27999203, 2017). "Our study therefore justifies further analysis of the correlation between secreted SPINK6 activity and tumor development in HCC patients." (PMID 27999203, 2017). "In addition, TMA staining results showed that the expression level of SPINK6 increased with tumor stage in HCC tissues, and it was positively correlated with BAP31 expression." (PMID 39990675, 2025). "As SPINK6 is a secretory protein, the extracellular protein level may be decreased because of tumor development." (PMID 27999203, 2017). "When comparing gene expression profiles between the original QGY-7703 cells and those resistant to the H-1PV superinfection, we found that SPINK6 is one of the factors highly expressed in the resistant cells, indicating that SPINK6 is a putative tumor suppressor in hepatocytes." (PMID 27999203, 2017). "Our study suggests that the potential anti-tumor activity of SPINK6 inhibits ERK1/2 phosporylation." (PMID 27999203, 2017). "Our results have shown that SPINK6 is secreted into the extracellular space, where it may trigger some tumor suppressing signaling pathways to suppress the tumorigenic phenotypes of the HCC cells." (PMID 27999203, 2017). "Together, these results strongly suggested that SPINK6 may be a tumor suppressor and its expression may be reduced as HCC develops." (PMID 27999203, 2017). "Quantitation of the immunostaining results confirmed that the SPINK6 protein levels were reduced in all tumor tissues grouped as period I–II and II–III (1.40 ± 0.45 and 1.24 ± 0.47, respectively), while those in the adjacent normal tissues were relatively high (2.38 ± 0.51)." (PMID 27999203, 2017). "Our study supports that SPINK6 is an important tumor suppressor in liver, and further investigations may help develop more effective diagnostic and therapeutic approaches." (PMID 27999203, 2017). "To further confirm that the potential tumor suppression role of SPINK6 requires ERK1/2, we incubated the cells with excess PMA which could excite continuous phosphorylation of ERK1/2 beforehand and then tested whether SPINK6 could still suppress the tumorigenic phenotypes." (PMID 27999203, 2017). "Notably, SPINK6 expression was nearly undetectable in tumor tissues of advanced stages." (PMID 27999203, 2017). "As expected, overexpression of SPINK6 reduced cell migration, invasion and proliferation of all HCC cell lines, and significantly reduced tumor growth when the HuH7 and SK-Hep-1 cells were implanted into nude mice." (PMID 27999203, 2017). "Common up-regulated genes are related to transcription regulation (HMBOX1, LINC00340, NEXN-AS1), immune response (CD86, IL6, IFIT2) and the last two are potential tumor suppressors (LRRC2 and SPINK6)." (PMID 28035074, 2017). "In summary, we determined the high expression of BAP31, ELAVL1 and SPINK6 in HCC tissues, knockdown of BAP31, ELAVL1 or SPINK6 recovered the cell polarity and inhibited the invasion and migration in HCC cells, and suppressed the tumor formation and lung metastasis in mice models." (PMID 39990675, 2025).
tumor (continued). "In addition, tumor weight data were as expected: mice receiving BAP31, ELAVL1 or SPINK6 knockdown HCC cells had lighter tumors, while SPINK6 overexpression partially compensated for the decrease of tumor weight caused by depletion of BAP31 or ELAVL1." (PMID 39990675, 2025). "The staining intensity of SPINK6 in tumor cells was scored negative, weak (1+), moderate (2+) or strong (3+)." (PMID 38157249, 2023). "The putative tumor suppression role of SPINK6 is, however, independent of its protease inhibitory activity." (PMID 27999203, 2017). "The results suggested that the potential anti-tumor activity of SPINK6 does not require its inhibition of the KLK proteases." (PMID 27999203, 2017). "Moreover, tumor growth curve showed that BAP31, ELAVL1 or SPINK6 knockdown decreased tumor growth, while SPINK6 overexpression could counteract this improvement." (PMID 39990675, 2025).
infection (3 papers, 2022 to 2025). The state of being infected such as from the introduction of a foreign agent such as serum, vaccine, antigenic substance or organism. "We further verified SPINK6 inhibition of protease‐driven viral growth in more susceptible A549 cells upon infection with H1N1/pdm." (PMID 34826211, 2022). "Later, SPINK6 was also shown to be expressed in bronchial epithelial cells and further upregulated in airway organoids following infection with Influenza A virus." (PMID 38543698, 2024). "Taken together, these results identify SPINK6 as an infection-inducible protease inhibitor that restricts Influenza A virus replication in the respiratory tract and determines susceptibility to viral infection in humans." (PMID 38543698, 2024).
cancer (2 papers, 2017 to 2025). A tumor composed of atypical neoplastic, often pleomorphic cells that invade other tissues. "We also determined the protein levels of SPINK6 by immunostaining hepatocarcinoma tissues and the matched para-carcinoma normal tissues in a tissue microarray consisting of 48 patient samples." (PMID 27999203, 2017). "There are few studies on SPINK6 in cancer, and the results are inconsistent." (PMID 39990675, 2025). "SPINK6 is a serine protease inhibitor, and can promote epithelial-mesenchymal transition (EMT) in cancer cells." (PMID 39990675, 2025).
cardiovascular disease (1 paper, 2025). "Furthermore, ECI2, KLK7, and SPINK6 appear to be linked to other forms of cardiovascular disease rather than CIHD." (PMID 41283645, 2025).
SPINK6 also shares sentences with these, for which no sentence is quoted: psoriasis (2 papers); coronary artery disease (1); nasopharyngeal squamous cell carcinoma (1); occult macular dystrophy (1); retinitis pigmentosa (1); squamous cell carcinoma (1).